TSPAN13 (tetraspanin 13)
Synonyms: NET6; TM4SF13; NET-6
Tractability: Antibody: its Gene Ontology location is reachable by antibodies, with high confidence; UniProt predicts a signal peptide or a membrane-spanning region. PROTAC: its protein half-life has been measured.
Gene: Protein-coding gene on chromosome 7 (16,753,745 to 16,784,536, forward strand). Ensembl gene ENSG00000106537.
Subcellular location: Membrane
Subcellular location (Human Protein Atlas): Nucleoplasm
Gene Ontology:
Molecular function: protein binding; calcium channel regulator activity
Cellular component: membrane; plasma membrane
Genetic constraint (gnomAD): Loss-of-function variants: 13 observed, 18.14 expected, observed/expected ratio (o/e) 0.72, 90% interval 0.47 to 1.14. The upper end of that interval is the gene's LOEUF score, 1.14, which puts it in group 4 of 6, group 1 being the genes least tolerant of losing a copy. Missense variants: 162 observed, 213.24 expected, observed/expected ratio (o/e) 0.76, 90% interval 0.67 to 0.87. Synonymous variants: 100 observed, 85.61 expected, observed/expected ratio (o/e) 1.17, 90% interval 0.99 to 1.38.
Homologues: Orthologues: chimpanzee TSPAN13 (100% identical), dog TSPAN13 (97% identical), macaque TSPAN13 (97% identical), mouse Tspan13 (96% identical), pig TSPAN13 (96% identical), rat Tspan13 (95% identical), guinea pig TSPAN13 (95% identical), tropical clawed frog tspan13 (79% identical), zebrafish tspan13b (70% identical), zebrafish tspan13a (67% identical). Paralogues in human: TSPAN31 (59% identical), CD82 (26% identical), CD37 (26% identical), TSPAN1 (26% identical), CD63 (25% identical), TSPAN3 (25% identical), TSPAN8 (25% identical), TSPAN12 (24% identical), TSPAN17 (24% identical), TSPAN4 (24% identical), TSPAN5 (23% identical), CD9 (22% identical), and 20 more.
Diseases named in the same sentence as TSPAN13 in open-access papers:
TSPAN13 is named in the same sentence as 30 diseases in open-access papers, as found by Europe PMC text mining. Sharing a sentence is not in itself a finding about the gene and the disease. The quoted sentences say what the papers report.
breast carcinoma (11 papers, 2017 to 2025). "Mechanistically, TSPAN13 was identified as a direct target of miR‐4732‐5p and low expression of TSPAN13 was associated with poor survival of breast cancer patients." (PMID 30701690, 2019). "TSPAN13 reduces proliferation and invasion and enhances apoptosis of breast cancer cells in vitro and in vivo." (PMID 36358336, 2022). "TSPAN13 in breast cancer cells hinders growth and invasion, as well as elevating apoptosis in vitro and in vivo." (PMID 36140731, 2022). "MiR-4732-5p played a major oncogenic role in breast cancer progression by targeting TSPAN13, and potentially served as an unfavorable biomarker with miR-448, miR-486, miR-516, and miR-1911 in lung squamous cell carcinoma." (PMID 33910598, 2021). "For example, TSPAN13 has been shown to be a tumor suppressor gene in breast cancer, while TSPAN1 can inhibit the migration of alveolar epithelial cells and the EMT process." (PMID 32694936, 2020). "Ectopic expression of TSPAN13 in breast cancer cells has been reported to inhibit anchorage independent growth, increase apoptosis and reduce invasion." (PMID 30602372, 2019). "While the expression of TSPAN13 in prostate cancer and glioma is known to be elevated, there is only one study on TSPAN13 in breast cancer." (PMID 31182966, 2019). "As shown in BioProfiling, low expression of TSPAN13 predicted poor survival of breast cancer patients (GEO database: GSE250665, n = 507, P = 0.000546)." (PMID 30701690, 2019). "MiR‐4732‐5p promoted breast cancer cell proliferation, migration and invasion at least partially via down‐regulation of TSPAN13." (PMID 30701690, 2019). "Similarly, studies have shown that miR-4732-5p promotes breast cancer progression by targeting TSPAN13." (PMID 39903772, 2025). "It mentioned that TSPAN13 was upregulated in breast cancer cells." (PMID 31182966, 2019). "Thus, our current findings provide evidence to improve characterization of the miR‐4732‐5p/TSPAN13 regulatory axis in breast cancer." (PMID 30701690, 2019). "This is the first study to reveal that miR‐4732‐5p may promote breast cancer progression at least partially by directly targeting TSPAN13." (PMID 30701690, 2019). "Expression of human TSPAN13 is downregulated both with age and in breast cancers." (PMID 28401650, 2017). "In our results, the expression levels of TSPAN1, TSPAN13, and TSPAN15 in breast cancer were all increased." (PMID 31182966, 2019). "Our TSPAN1 results are consistent with those previously reported, so we speculate that TSPAN13 and TSPAN15 may be potential cancer-related genes for breast cancer." (PMID 31182966, 2019).
papillary thyroid cancer (3 papers, 2019 to 2025). "The expression of TSPAN13 is also associated with poor prognosis of papillary thyroid cancer, pancreatic cancer, lung adenocarcinoma, and bladder cancer." (PMID 35277124, 2022). "Research has found that downregulation of TSPAN13 by miR-369-3p can inhibit the proliferation of papillary thyroid cancer cells." (PMID 39903772, 2025). "miR-369-3p can inhibit cell proliferation in papillary thyroid cancer by down-regulating the target gene, TSPAN13." (PMID 31337985, 2019).
breast tumors (2 papers, 2019 to 2024). "Specifically in breast tumors, there are few publications on the expression profile and functional role of TSPAN13, and the published data are contradictory." (PMID 38611080, 2024). "However, an increased expression of TSPAN13 in breast tumors compared to benign tissue has been considered a potential new biomarker for BC and a helpful agent in clinical outcomes." (PMID 38611080, 2024). "Based on these factors, LRRC15, EFNA3, TSPAN13, and CA12 were identified as transcripts with higher expression and prevalence levels in breast tumors, with low expressions in most of the control tissues." (PMID 38611080, 2024). "TSPAN13 expression is significantly reduced in estrogen negative, Her2 negative and basal-like breast tumors." (PMID 30602372, 2019).
glioma (2 papers, 2019 to 2025). A benign or malignant brain and spinal cord tumor that arises from glial cells (astrocytes, oligodendrocytes, ependymal cells). "While our study primarily focused on identifying TSPAN13 as a novel prognostic marker for TMZ resistance in glioma, further research is needed to determine the underlying mechanisms and regulatory pathways associated with TSPAN13 in more detail." (PMID 39903772, 2025). "Our results revealed that TSPAN13 knockdown indeed increased TMZ-induced DNA damage in glioma cells and inhibited the TMZ resistance of GBM in vivo." (PMID 39903772, 2025). "We observed that an increase in TSPAN13 expression correlated with an increase in the grade of glioma." (PMID 39903772, 2025). "The results revealed that TSPAN13 protein expression was significantly lower in WHO grade II gliomas than in higher-grade gliomas (WHO III and IV)." (PMID 39903772, 2025). "At the same time, analysis via the GlioVis database revealed that an increase in TSPAN13 expression correlated with an increase in glioma grade in the TCGA cohorts." (PMID 39903772, 2025). "Further experiments revealed that TSPAN13 knockdown increased glioma cell sensitivity to carmustine, another alkylating agent, while showing no significant impact on sensitivity to the apoptosis inducer cisplatin or the EGFR inhibitor gefitinib." (PMID 39903772, 2025). "Therefore, we focused our subsequent investigations on validating the role of TSPAN13 in glioma progression and drug resistance." (PMID 39903772, 2025). "To assess the potential role of TSPAN13 in influencing the efficacy of various antitumor drugs against glioma, we performed preliminary tests with drugs known for their cytotoxic effects on glioma." (PMID 39903772, 2025). "We assessed cell proliferation, migration, and invasion capabilities through in vitro assays (including CCK-8, Edu, wound healing, and transwell assays) and quantitatively analyzed TSPAN13 expression levels in clinical glioma samples using tissue microarray immunohistochemistry." (PMID 39903772, 2025). "Among the 12 TMZR-RDEGs identified in our study, TSPAN13 was found to be the only gene not previously reported in glioma research." (PMID 39903772, 2025). "Among these 12 TMZR-RDEGs, TSPAN13 is the only gene that has not yet been specifically investigated in glioma, making it the focal target for our subsequent research." (PMID 39903772, 2025).
prostate carcinoma (2 papers, 2019 to 2025). A carcinoma that arises from epithelial cells of the prostate gland. "In prostate cancer, studies have found that TSPAN13 is highly expressed in 80% of prostate cancer samples, suggesting that it may play a promotive role in the development of prostate cancer." (PMID 39903772, 2025).
triple-negative breast carcinoma (2 papers, 2019 to 2024). An invasive breast carcinoma which is negative for expression of estrogen receptor (ER), progesterone receptor (PR), and human epidermal growth factor receptor 2 (HER2). "Therefore, TSPAN13 is presently considered as a diagnostic and therapeutic target for triple-negative breast cancer." (PMID 38611080, 2024).
asthma (1 paper, 2020). "In addition, other identified genes were LRRC48 and CETN2 in asthma-COPD, COL15A1, GIMAP6, and JAM2 in asthma-IPF, along with LMO7, TSPAN13, LAMA3, and ANXA3 in COPD-IPF." (PMID 31952466, 2020). "These genes included RBM42, STX5, and TRIM41 in asthma, CYP27A1, GM2A, LGALS9, SPI1, and NLRC4 in COPD, ATF3, PPP1R15A, ZFP36, SOCS3, NAMPT, and GADD45B in IPF, LRRC48 and CETN2 in asthma-COPD, COL15A1, GIMAP6, and JAM2 in asthma-IPF and LMO7, TSPAN13, LAMA3, and ANXA3 in COPD-IPF." (PMID 31952466, 2020).
colorectal cancer (1 paper, 2025). A primary or metastatic malignant neoplasm that affects the colon or rectum. "In spatial transcriptomics studies of colorectal cancer, molecules including TSPAN13 were found to be specifically highly expressed in tumor regions, indicating their potential roles in tumor development." (PMID 39903772, 2025).
coronary atherosclerosis (1 paper, 2022). Atherosclerosis of the coronary vasculature. "Three significant DEGs—TOX, RasGRP3, and TSPAN13—were selected for IHC analysis based on their high fold changes and possible biological functions in the development of early coronary atherosclerosis to validate the bioinformatics analysis results." (PMID 36140731, 2022).
endometrial cancer (1 paper, 2021). Primary or metastatic malignant neoplasm involving the endometrium (mucous membrane that lines the endometrial cavity). "In addition, a positive correlation was found between the expression of NUCB2/NESF-1 and EMT-related genes such as desmoplakin (DSP), Integrin Subunit Alpha V (ITGAV), metalloproteinase 3 (MMP3), tetraspanin 13 ( TSPAN13), and Cadherin 2 (CDH2) in endometrial cancer cells." (PMID 34361082, 2021).
glioblastoma (1 paper, 2025). The most malignant astrocytic tumor (WHO grade IV). "To further validate the impact of TSPAN13 on tumor drug resistance in vivo, we constructed an orthotopic glioblastoma xenograft model." (PMID 39903772, 2025). "To elucidate the biological function of TSPAN13 in glioblastoma multiforme (GBM) cells, we knocked down TSPAN13 in the U87 and U251 cell lines using two specific siRNAs." (PMID 39903772, 2025).
metastatic tumor (1 paper, 2024). "The TSPAN13, TSPAN31, and UPK1B genes were upregulated in the fibroblast compartment of metastatic tumor." (PMID 38255741, 2024). "The upregulation of TSPAN13, TSPAN31, and UPK1B genes in the fibroblast compartment of metastatic tumor suggests their potential significance in the context of tumor–fibroblast interactions, metastasis, and the distinct characteristics of the metastatic microenvironment." (PMID 38255741, 2024).
mucinous tumors (1 paper, 2024). "TSPAN13 is overexpressed in infiltrating ductal, lobular, mixed, and mucinous tumors." (PMID 38611080, 2024).
osteosarcoma (1 paper, 2021). A usually aggressive malignant bone-forming mesenchymal neoplasm, predominantly affecting adolescents and young adults. "Furthermore, only one report regards promotion of human osteosarcoma cells progression by enhancing TSPAN13 expression." (PMID 34202288, 2021).
virus infection (1 paper, 2022). "TSPAN13 (also known as NET-6) belongs to a superfamily of small transmembrane proteins that are implicated in cell migration, proliferation, signal-transduction, intracellular trafficking, and virus infection." (PMID 36140731, 2022).
tumor (13 papers, 2012 to 2025). "Through GSEA enrichment analysis, we found that TSPAN13 is associated with multiple tumor-related signaling pathways." (PMID 39903772, 2025). "In vivo orthotopic mouse xenograft models also confirmed that knocking down TSPAN13 significantly increases the tumor's sensitivity to temozolomide." (PMID 39903772, 2025). "Taken together, TSPAN13 knockdown inhibited tumor proliferation and migration, as well as the activation of tumor-related signaling pathways." (PMID 39903772, 2025). "A key finding of our research is the important role of TSPAN13: its downregulation in GBM cells suppresses tumour proliferation, migration, invasion, and resistance to TMZ." (PMID 39903772, 2025). "We found that knocking down TSPAN13 in tumor cells significantly increased their sensitivity to TMZ." (PMID 39903772, 2025). "TSPAN13 mRNA expression levels were also increased in several tumor tissues, including BRCA (except TNBC), BLCA, ESCA, HNSC, KIRC, PRAAD, STAD, THCA, and UCED." (PMID 38611080, 2024). "CD9, CD151, TSPAN1, TSPAN3, TSPAN8, and TSPAN13 displayed specific overexpression in the tumor compartment, indicating potential roles in tumor growth." (PMID 38255741, 2024). "Tspan1, Tspan11, Tspan13, Tspan28, Tspan29, and Tspan30 have been identified as biomarkers for tumor diagnosis and prognosis, while Tspan8, Tspan24, and Tspan27 show potential as biomarkers." (PMID 38649381, 2024). "In the tumor compartment, several tetraspanins (CD9, CD151, TSPAN1, TSPAN3, TSPAN8, and TSPAN13) were specifically overexpressed, suggesting their involvement in tumor growth and proliferation in stage 4 primary CC." (PMID 38255741, 2024). "In TβRII KO tumor epithelium compared with TβRIIfl/fl epithelium, Igfbp4 and Tspan13 expression was upregulated while Col1α2, Bmp7, Gng11, Vcan, Tmeff1, and Dsc2 expression was downregulated." (PMID 22748014, 2012). "TSPAN13 has been shown to be a tumor suppressor gene in breast cancer." (PMID 38213729, 2024). "In addition, some members of the four-transmembrane protein family, such as TSPAN and TSPAN13, have been shown to affect tumor metastasis and progression, but there are few studies on these functions." (PMID 32694936, 2020). "TTK, MCM2, CLDN7 and TSPAN13 promote tumor cell proliferation and their overexpression could stimulate drug resistance." (PMID 26515599, 2015). "Our analysis consistently confirmed the increased expressions of LRRC15, EFNA3 TSPAN13, and CA12 in tumor samples, consistent with TCGA data findings from the DS and VS cohorts." (PMID 38611080, 2024). "Comparing the tumor samples with metastatic ones, we observed significant results for LRRC15, TSPAN13, and CA12 as determined by Dunn’s test (p < 0.05)." (PMID 38611080, 2024). "As a result, we identified four membrane proteins—LRRC15, EFNA3, TSPAN13, and CA12—that demonstrated high expressions in BC tissues compared to adjacent non-tumor breast tissues and other healthy samples, with a few exceptions." (PMID 38611080, 2024).
cancer (9 papers, 2017 to 2025). A tumor composed of atypical neoplastic, often pleomorphic cells that invade other tissues. "Age‐dependent loss of TSPAN13 may contribute to cancer risk by elevating HIF‐1‐mediated transcription." (PMID 28401650, 2017). "Recent studies have increasingly highlighted the importance of TSPAN13 in various human cancers, as it is strongly correlated with poor patient prognosis." (PMID 39903772, 2025). "CD81, CD9, TSPAN31, and TSPAN13 are also reported to facilitate cancer cell invasion and metastasis." (PMID 36941633, 2023). "However, multiple studies have shown the involvement of TSPAN13 in various human cancers, highlighting its important role." (PMID 39903772, 2025). "TSPAN13 was of particular interest in light of its reported roles in suppressing cancer cells progression. qRT‐PCR and Western blot were performed to investigate whether miR‐4732‐5p altered TSPAN13 gene and protein expression." (PMID 30701690, 2019). "Taken together, these findings suggest that LRRC15, EFNA3, TSPAN13, and CA12 can serve as potential biomarkers for improving cancer diagnosis screening and as suitable targets for therapy with reduced side effects and enhanced efficacy." (PMID 38611080, 2024). "TSPAN13 (Tetraspanin 13), identified as one of the 12 TMZ resistance-related differentially expressed genes (TMZR-RDEGs) in our study, has been reported to play a role in the progression of various cancers." (PMID 39903772, 2025). "Importantly, the overexpression of LRRC15, EFNA3, TSPAN13, and CA12 was observed in tissues at both early and advanced stages of cancer, indicating that these proteins hold promise as targets for early diagnosis." (PMID 38611080, 2024). "As a general feature, the expression of epithelial genes (e.g. TJP3, TSPAN13, CLDN7 and EPCAM) was positively correlated with the expression of AGR2/3 and the expression of mesenchymal genes (e.g. VIM and MSN) was negatively correlated, with specific correlations according to cancer type." (PMID 35857928, 2022). "We assessed the mRNA expression levels of LRRC15, EFNA3, TSPAN13, and CA12 in diverse cancer tissues and compared them to normal tissue using the TIMER2.0 database." (PMID 38611080, 2024).
metabolic disease (1 paper, 2024). A congenital disorder (due to inherited enzyme abnormality) or acquired (due to failure of a metabolically important organ) disorder resulting from an abnormal metabolic process. "Other hub RMITRGs, such as HES1, TMBIM6, TSPAN13, and VMP1, also showed significant associations with metabolic diseases, highlighting the diverse molecular pathways involved in T2D." (PMID 39926598, 2024).
TSPAN13 also shares sentences with these, for which no sentence is quoted: acute myeloid leukaemia (1 paper); Atrophy (1); bladder cancer (1); hepatoma (1); invasive breast carcinoma (1); leukaemia (1); lung adenocarcinoma (1); lung squamous cell carcinoma (1); lymphoma (1); neurodevelopmental disorder (1); pancreatic cancer (1); skin cancer (1).